STARD4 (StAR related lipid transfer domain containing 4)
Description:
Involved in the intracellular transport of cholesterol. Binds cholesterol or other sterols.
Tractability: Antibody: the Human Protein Atlas places it where antibodies can reach. PROTAC: ubiquitination databases record sites on it.
Gene: Protein-coding gene on chromosome 5 (111,495,551 to 111,512,590, reverse strand). Ensembl gene ENSG00000164211.
Subcellular location: Cytoplasm; Endoplasmic reticulum
Subcellular location (Human Protein Atlas): Plasma membrane
Pathways (Reactome):
Metabolism: Pregnenolone biosynthesis
Gene Ontology:
Molecular function: cholesterol binding; cholesterol transfer activity; protein binding; lipid binding
Biological process: cholesterol import; cholesterol transport involved in cholesterol storage; intracellular cholesterol transport; positive regulation of bile acid biosynthetic process; positive regulation of cholesterol metabolic process
Cellular component: cytoplasm; cytoplasmic vesicle; cytosol; endoplasmic reticulum
Genetic constraint (gnomAD): Loss-of-function variants: 27 observed, 22.49 expected, observed/expected ratio (o/e) 1.2, 90% interval 0.88 to 1.65. The upper end of that interval is the gene's LOEUF score, 1.65, which puts it in group 6 of 6, group 1 being the genes least tolerant of losing a copy. Missense variants: 218 observed, 242.31 expected, observed/expected ratio (o/e) 0.9, 90% interval 0.81 to 1.01. Synonymous variants: 78 observed, 76.52 expected, observed/expected ratio (o/e) 1.02, 90% interval 0.85 to 1.23.
Homologues: Orthologues: chimpanzee STARD4 (99% identical), macaque STARD4 (99% identical), rabbit STARD4 (89% identical), pig STARD4 (89% identical), rat Stard4 (89% identical), mouse Stard4 (87% identical), dog STARD4 (86% identical), guinea pig STARD4 (86% identical), tropical clawed frog stard4 (65% identical), zebrafish stard4 (58% identical), Caenorhabditis elegans K02D3.2 (26% identical), Drosophila melanogaster Start1 (23% identical), and 1 more. Paralogues in human: STARD5 (33% identical), STARD6 (28% identical), STARD3 (26% identical), STAR (20% identical), STARD3NL (7% identical).
Diseases named in the same sentence as STARD4 in open-access papers:
STARD4 is named in the same sentence as 13 diseases in open-access papers, as found by Europe PMC text mining. Sharing a sentence is not in itself a finding about the gene and the disease. The quoted sentences say what the papers report.
hepatocellular carcinoma (3 papers, 2024 to 2025). A malignant tumor that arises from hepatocytes. "Research has highlighted the association of STARD4 with the development of multiple malignancies, such as hepatocellular carcinoma, breast cancer, head and neck squamous cell carcinoma, and skin cutaneous melanoma." (PMID 41331871, 2025). "Additionally, SREBF2 facilitated the upregulation of STARD4 by directly binding to its promoter region, thereby inducing elevated levels of mitochondrial cholesterol, and contributing to the resistance of hepatocellular carcinoma against sorafenib." (PMID 38840241, 2024).
prostate carcinoma (3 papers, 2019 to 2025). A carcinoma that arises from epithelial cells of the prostate gland. "In another study, researchers constructed a miRNA-mRNA regulatory network containing miR-106b-5p to identify genes such as TMEM100, FRMD6, NBL1, and STARD4 for the diagnosis and prognosis of prostate cancer patients." (PMID 38818039, 2024).
breast carcinoma (2 papers, 2023 to 2024). "Some researchers have reported that STARD4 is highly expressed in breast cancer tissues and promotes tumour progression by regulating cholesterol metabolism." (PMID 38556542, 2024). "High expression of STARD4 in breast cancer has also been reported, and cell function experiments show that knockdown of STARD4 significantly inhibits the proliferation and migration of breast cancer." (PMID 37090107, 2023).
acute lymphoblastic leukemia (1 paper, 2016). Leukemia with an acute onset, characterized by the presence of lymphoblasts in the bone marrow and the peripheral blood. "It has recently been demonstrated that STARD4 expression could be used as poor prognosis gene in a six genes signature that defines aggressive subtypes in adult acute lymphoblastic leukemia." (PMID 28027290, 2016).
head and neck squamous cell carcinoma (1 paper, 2023). A squamous cell carcinoma that arises from any of the following anatomic sites: lip and oral cavity, nasal cavity, paranasal sinuses, pharynx, larynx, and salivary glands. "In conclusion, SREBF1 possibly through upregulation of STARD4 and affects immune infiltration to promote proliferation, migration and inhibit apoptosis in head and neck squamous cell carcinoma." (PMID 37090107, 2023). "This suggests that SREBF1 may promote the proliferation and migration of head and neck squamous cell carcinoma through STARD4." (PMID 37090107, 2023).
Hepatitis (1 paper, 2025). Inflammation of the liver. "The analysis results revealed that the mRNA expression level of STARD4 was significantly correlated with tumor size (P = 0.032), alpha-fetoprotein levels (P = 0.032), hepatitis (P = 0.005), TNM stage (P < 0.001), and microvascular infiltration (P < 0.001)." (PMID 40831538, 2025).
osteoarthritis (1 paper, 2023). A noninflammatory degenerative joint disease occurring chiefly in older persons, characterized by degeneration of the articular cartilage, hypertrophy of bone at the margins and changes in the synovial membrane. "Notably, the identified here interactions between hsa-let7b/i, hsa-miR-221/222-3p, hsa-miR-302c, hsa-miR-181a, hsa-miR-331 with target genes HMGA2, IGF2BP3, STARD4, and APOL6 could prove to be the necessary tools that will convey iMSCs into the ideal mean for cell therapy in osteoarthritis." (PMID 37443790, 2023).
osteosarcoma (1 paper, 2025). A usually aggressive malignant bone-forming mesenchymal neoplasm, predominantly affecting adolescents and young adults. "Consistent with our observations, previous research has also documented that down-regulation of STARD4 heightened intracellular free cholesterol levels and impeded sterol transport in human U2OS osteosarcoma cells." (PMID 40831538, 2025).
cancer (4 papers, 2023 to 2025). A tumor composed of atypical neoplastic, often pleomorphic cells that invade other tissues. "The expression of the TGF-β-regulated genes (DHCR7, FABP5, HMGCR, MVD, SQLE and STARD4) was further correlated with clinical features using cancer patient datasets." (PMID 39910665, 2025). "Among them, five genes (FGG, MYH15, STARD4, SYTL4, and TMEM267) were first associated with cancer procession, while the other three (KRT81, KRT6A, and KRT13) have previously been confirmed to be related to cancer metastasis and migration." (PMID 37817112, 2023). "STARD4, an efficient cholesterol transporter, facilitates cholesterol transportation to the endoplasmic reticulum, fostering the production of cholesteryl ester, which appears to function as a reservoir of cholesterol that cancer cells can tap under increased demand." (PMID 40831538, 2025).
tumor (4 papers, 2023 to 2025). "Herein, we present the initial comprehensive investigation into the tumor-promoting function and mechanism of STARD4 in HCC." (PMID 40831538, 2025). "In conclusion, these data from animal studies suggests that STARD4 knockdown suppresses tumorigenesis and enhances the anti-tumor effect of lenvatinib in vivo by inhibiting EGFR/PI3K/AKT signaling pathway." (PMID 40831538, 2025). "In summary, both the in vitro and in vivo results strongly demonstrated that STARD4 markedly suppresses PCa cell proliferation and restrains xenograft tumour progression." (PMID 41331871, 2025). "While STARD4 has been recognized for its role in regulating lipid metabolism in various types of tumours, its specific impact on PCa has remained less clear." (PMID 41331871, 2025). "Consistent with the in vitro findings, xenograft tumours with upregulated STARD4 expression presented reduced lipid accumulation within the cytoplasm, whereas STARD4 silencing led to a significant increase in lipid accumulation." (PMID 41331871, 2025). "STARD4 knockdown exhibited a significant suppressing effect on the growth of the subcutaneous tumor and dramatically enhanced the sensitivity of HCC to lenvatinib, according to the tumor weight and volume in each group." (PMID 40831538, 2025). "In contrast, STARD4 overexpression led to the significant inhibition of tumour growth when it was combined with enzalutamide treatment." (PMID 41331871, 2025). "Taken together, these findings indicate that STARD4 functions as a tumor-promoting factor to enhance the proliferation, migration, invasion, and angiogenesis of HCC cells." (PMID 40831538, 2025). "Tumor volume and tumor weight were measured, and the data showed that the tumor growth rate of the STARD4 overexpression group (STARD4-OE) was significantly higher than that of the control group." (PMID 40831538, 2025). "Enhanced phosphorylation of EGFR, PI3K, and AKT were displayed in STARD4 overexpression tumor tissues." (PMID 40831538, 2025). "STARD4 overexpression in PCa models significantly diminished the tumour growth rate, size, and weight." (PMID 41331871, 2025). "By analyzing clinical samples from patients diagnosed with HCC, we observed an up-regulation of both mRNA and protein expression of STARD4 in tumor tissues compared with adjacent normal tissues." (PMID 40831538, 2025). "In summary, STARD4 functions as a tumour suppressor in PCa by regulating cholesterol metabolism and modulating AR signalling." (PMID 41331871, 2025). "Quantitative reverse transcription PCR revealed that among 52 clinical samples from patients diagnosed with HCC, 46 pairs of tumor tissues showed significant up-regulation of STARD4 mRNA expression, with only 6 pairs showing down-regulation." (PMID 40831538, 2025). "The results revealed that STARD4 overexpression decreased lipid accumulation in tumour tissues, whereas STARD4 knockdown resulted in increased lipid accumulation." (PMID 41331871, 2025). "Immunohistochemistry analysis showed that KI67 expression increased in STARD4 overexpressed tumors compared with the control group, indicating that STARD4 exerted a promoting effect on tumor growth." (PMID 40831538, 2025). "Meanwhile, results from immunohistochemistry assays showed that STARD4 was widely distributed in the cytoplasm, and the protein levels in tumor tissue was higher than that in adjacent normal tissues." (PMID 40831538, 2025). "In conclusion, our study offers profound insights into the diverse biological functions of STARD4 in PCa, including its roles in inhibiting tumour growth, regulating lipid metabolism, and modulating the AR signalling pathway." (PMID 41331871, 2025). "RT‒qPCR, western blot analysis, and IHC staining were performed to evaluate STARD4 expression, while Kaplan–Meier survival analysis, Gleason score, and tumor stage were performed to assess its clinical significance in PCa." (PMID 41331871, 2025).
tumor (continued). "Collectively, these results demonstrate that STARD4 exerts tumor-promoting effects through the activation of the EGFR/PI3K/AKT pathway in HCC cells." (PMID 40831538, 2025). "In vivo experiments corroborated these findings, demonstrating that STARD4 overexpression significantly restrains the growth of enzalutamide-resistant tumours." (PMID 41331871, 2025). "It was found that STARD4 was significantly up-regulated in tumor tissues compared with the nearby tissues." (PMID 40831538, 2025). "Further analysis of the TCGA database revealed that SREBF1 and STARD4 expression is significantly higher in HNSC tumor tissues than in adjacent normal tissues." (PMID 37090107, 2023). "Analysis of the UALCAN database indicated that the expression of SREBF1 and STARD4 correlated with sample type, tumor stage, lymph node stage, and tumor grade." (PMID 37090107, 2023). "Additionally, we have identified that STARD4 impairs the anti-tumor effect of lenvatinib in HCC, while the down-regulation of STARD4 enhances sensitivity to lenvatinib." (PMID 40831538, 2025). "Additionally, ORO staining revealed that, compared with the other treatments, the combination of STARD4 overexpression and enzalutamide treatment resulted in a significant reduction in LD size within tumour tissues." (PMID 41331871, 2025). "Additionally, low STARD4 expression was correlated with tumour progression, metastasis, and high Gleason scores." (PMID 41331871, 2025). "Considering that increased intratumoural androgen synthesis is a critical factor in PCa progression and that cholesterol serves as a vital precursor for androgen synthesis, we hypothesized that STARD4 influences androgen levels within tumour cells." (PMID 41331871, 2025). "Our findings identify STARD4 as a promising therapeutic target for reversing enzalutamide resistance in PCa while also providing novel insights for future research on lipid metabolism within the tumour microenvironment." (PMID 41331871, 2025). "EGFR inhibitor erlotinib could suppress the promotion of STARD4 on the progression of HCC, which further reinforced the idea that STARD4 exerts tumor-promoting effects and enhances the resistance to lenvatinib through activation of EGFR/PI3K/AKT pathway in HCC cells." (PMID 40831538, 2025). "To evaluate the role of STARD4 in HCC, we first analyzed its expression in HCC tissues and the matched non-tumor liver tissues." (PMID 40831538, 2025). "To further investigate the role of STARD4 in the activation of EGFR/PI3K/AKT pathways, we detected the protein level of p-EGFR, p-PI3K, and p-AKT in the tumor tissues from the xenograft nude mice model." (PMID 40831538, 2025). "Analysis of clinical samples from HCC patients revealed increased expression of both STARD4 and EGFR in tumor tissues, with a strong correlation between STARD4 expression and malignancy progression." (PMID 40831538, 2025). "A significant positive correlation between STARD4 and EGFR mRNA expression was found in tumor tissue samples obtained from HCC patients." (PMID 40831538, 2025). "In our study, we discovered a substantial positive correlation between STARD4 and EGFR mRNA expression in tumor tissue samples obtained from HCC patients." (PMID 40831538, 2025). "In vitro and in vivo studies demonstrated that STARD4 promoted HCC growth and hindered lenvatinib's anti-tumor effect, while STARD4 down-regulation exerted opposite effects." (PMID 40831538, 2025). "To further elucidate whether STARD4 regulates the progression and lenvatinib resistance of HCC via EGFR activation, we investigated the impact of EGFR inhibitor erlotinib on the tumor-promoting effect of STARD4 in HCC cells." (PMID 40831538, 2025).
STARD4 also shares sentences with these, for which no sentence is quoted: liver cancer (1 paper); neurological disorders (1); Obesity (1).